TGFB1 (transforming growth factor beta 1)
Diseases named in the same sentence as TGFB1 in open-access papers (continued):
Sharing a sentence is not in itself a finding about the gene and the disease.
cancer (continued). "β-catenin and TGFβ1 were detected by mass spectrometry whereas NFκB was not directly detected; however these proteins were further validated by tissue microarray analysis in a large number of samples demonstrating that they are highly overexpressed in cancer tissues." (PMID 28503055, 2016). "Furthermore, cancers that do not demonstrate mutations in any TGFβ1 signaling cascade members, show down-regulated levels of TGFBR2, demonstrating the oncogenic potential of TGFβ1 pathway." (PMID 23951322, 2013). "And the glycogen riskScore was significantly positively related with immunoinhibitors TGFB1, ICAM1 and CD276, and showed significantly negative relationship with immunostimulators TNFSF14 across pan-cancer." (PMID 39895799, 2025). "By contrast, stromal upstream regulators that were not estimated to be paracrine effector genes, such as DLL4, APP, and TGFB1, showed no significant increase in expression levels in KIRC cancer components compared with CCLE or GTEx." (PMID 35079698, 2021). "The results demonstrated that TGFβ1 is mainly expressed in the adjacent normal liver parenchyma (most likely hepatocytes) in CRCLM lesions and not in the cancer cells." (PMID 34376784, 2021). "Culture media recovered from EOC cell lines treated with vehicle (Ctl) or TGFβ1 (5 μg/ml) for 48 h did not proteolyze FBLN5, and cancer cell extracts did not metabolize FBLN5." (PMID 29581841, 2018). "However, according to our data, it is likely that TGFβ1 targeting will not be sufficient to abolish HGF production that, as already mentioned, is essential to drive cancer cell invasion." (PMID 36010567, 2022). "According to an ongoing study from our laboratory, RKIP/PEBP1 might have some effects on TGFB1-induced EMT and cancer metastasis (data not published)." (PMID 30115852, 2018). "Furthermore, stimulation with TGFβ1 upon overexpression of INHBA resulted in activation of the canonical and non-canonical pathways (for OE33 and FLO-1 cancer cells)." (PMID 26447543, 2015). "We find TGFB1 and TGFB3 gene are shown in normal HK genes group, which do not express in cancer." (PMID 23382867, 2013). "However, while Dex or TGFβ1 did not appreciably increase basal soft-agar colony formation over that observed in DCC alone, the GR antagonist, RU486, blocked soft-agar colony formation, demonstrating the GR-dependence of this cancer cell biology in 3D conditions." (PMID 32357907, 2020). "Interestingly, TGFβ1-mediated Erk5 activation did not involve Ras as FTS treatment did not alter Erk5 phosphorylation, thus emphasizing the cell type-specific nature of Erk5 signaling given that Ras involvement is inconsistent between a selection of cancer cell lines." (PMID 24795631, 2014).
infection (1,098 papers, 2004 to 2026). The state of being infected such as from the introduction of a foreign agent such as serum, vaccine, antigenic substance or organism. "Much has been discovered about the role of TGFB1 in HPV infection, such as the immunosuppression caused by TGFB1 favoring infection or the cytokine increasing by the action of viral oncoproteins." (PMID 36611878, 2022). "Of the CD3+ cells, a higher percentage of CD4+ T cells, but not CD8+ T cells, from IL-10-deficient mice produced TGFβ1 at both 5 and 7 days after infection compared to WT mice." (PMID 36016413, 2022). "The TGFβ1 pathway was also one of the most enriched terms in the set of differentially expressed genes associated with the infection." (PMID 36355906, 2022). "Higher induction of TGFβ1 are more associated with active disease (infection and failure or relapses after treatment) while the higher levels of EGF are associated with adequate response to treatment." (PMID 30333964, 2018). "Studies in αvβ6 knockout mice showed a deficiency in TGFβ1 activation by the epithelium and increased inflammation in response to injury and infection." (PMID 23547562, 2013). "This aberrant expression and activation of TGFβ1 in both the chronic ‘unstressed’ state and the acutely ‘stressed’ state may explain many of the pathophysiological features that characterize the ‘alcoholic lung’ and its susceptibility to infection and injury." (PMID 23547562, 2013). "For instance, males who later develop PCC can exhibit heightened TGF‐β signalling during acute infection, whereas females on track to develop PCC show reduced TGFB1 mRNA." (PMID 40492581, 2025). "Among the polymorphisms associated in one cohort which were tested in different cohorts but where the association was not replicated, we have IL18 rs2043055 with CCC, IFNG rs2430561 and infection, IL4 −590 and infection, TGFB1 −509 rs1800469 and infection." (PMID 40297326, 2025). "(A) Gene expression of healing markers Pdgfa, Tgfb1, and Egf 4 days post-infection (4 dpi) for uninfected and E. faecalis-infected 6–7 week-old C57BL/6 J mouse skin wounds, normalized to intact skin (n=6 for skin; n=8 for wounds; one-way ANOVA)." (PMID 38767331, 2024). "Consistently in vivo, KRAS (labeled with Cy3) in BMECs (labeled with anti-CD31-FITC) of mice treated with TGFβ1 prior infection was downregulated, in contrast to those left untreated." (PMID 38360663, 2024). "During infection, the immune response will upregulate genes that will aid in the fish’s survival, so the upregulation of tgfβ-1 would be counterproductive." (PMID 36986384, 2023). "Infection of HLF1 or WI38 fibroblast cell lines with RV-A16 or RV-A2 induced upregulation of TGFB1, MMP9, COL1A1, ADAM33, CHI3L1, LTC4S, and ACTA2." (PMID 37773065, 2023). "As we reported at earlier endpoints, Tgfb1 mRNA after MHV68 infection showed comparable levels between Cyb5r3fl/fl and SPC-KO mice with no change at 28 dpi after the intervention with the sGC agonist diets (data not shown)." (PMID 36749633, 2023). "Infection increased brain expression of both Tgfb1 and Tgfb3 mRNAs beginning at 3 days and a maximal 5–7 days after infection." (PMID 36016413, 2022). "To determine if these changes were unique to NSV, we also measured CNS levels of active TGFb1 and TGFb3 after infection with moderately virulent TE12 and relatively avirulent TE recombinant strains of SINV." (PMID 36016413, 2022). "TGFB1 was moderately upregulated in brain tissue during the final stage of the infection when compared to controls, likely mirroring the elevated serum concentration of anti-inflammatory TGF-β1." (PMID 35788177, 2022). "A significant decrease in representative pro-inflammatory factor (IL12B) expression with prolonged infection was observed while anti-inflammatory transforming growth factor beta-1 (TGF-β1) expression was continuously high during infection at 10°C." (PMID 35197977, 2022).
infection (continued). "Throughout all stages of infection, the increase in the myelination pathway is driven by the genes Hexb, Tgfb1, and Cxcr4." (PMID 33816350, 2021). "The serum levels of IL6, IL8, IL12 and Transforming growth factor beta 1 (TGFβ1) showed a more pronounced increase at the early infection stages with the PCV2 virus in the Laiwu pigs compared to YL pigs." (PMID 34407874, 2021). "Previous transcriptomic analyses revealed upregulation of TGFB1, cell death and Toll-like receptor signalling, T-cell activation, and inhibition of nitric oxide production in macrophages in response to infection." (PMID 34616397, 2021). "Transcript levels of Tgfb1 in the whole kidney were slightly higher at the time of infection and were significantly higher in TC‐treated mice 1‐day post‐infection." (PMID 32227630, 2020). "Upon infection with L. donovani amastigotes or promastigotes, anota2seq analysis identified augmented translational efficiency of the tumor growth factor-β 1 (Tgfb1) mRNA (top-right panel and S1 Table), which is highly dependent of eIF4A for its translation." (PMID 32479529, 2020). "These αSMA+, Gli1+, PDGFRβ + cells are visible in the post‐pyelonephritic scar as it forms and matures, and they become the predominant producers of TGFβ1 during resolving infection." (PMID 32227630, 2020). "These monocytes are then differentiated to macrophages that are involved in removing bacteria, preventing infection and contributing in collagen disposition once the inflammation is resolved with the increase of anti-inflammation cytokine such as TGFβ-1." (PMID 32872240, 2020). "TGFB1 maintains innate immune factor expression within a range that allows inhibition of bacterial growth during infection, a situation that is beneficial to host Salmonella resistance." (PMID 30541630, 2018). "We demonstrated that the expression of PDGF, EGF, FGF, and TGFβ1 was induced at ID15 during the establishment of the experimental infection by L. (V) braziliensis." (PMID 30333964, 2018). "Both TGFβ genes were significantly upregulated upon infection with Ct; TGFβ1 and TGFβ2 showed a 2- and 7-fold increase in mRNA, respectively." (PMID 28660176, 2017). "At 48 hours following infection, the cultures were treated with 2ng/mL of TGFβ1 for two days to induce EMT." (PMID 29228724, 2017). "Latently infected T-cells were prepared by infection of naïve CD4+ T-cells with HIV-1 NL4-3 followed by culture with IL-7/TGFβ-1 for 2 weeks, a condition modified based upon previous publications." (PMID 27049645, 2016). "ShMLL1 and shSET7/9 co-infection completely inhibited TGFβ1-induced TGFBIp mRNA levels compared with shMLL1 or shSET7/9 single infection, providing evidence that both MLL1 and SET7/9 mediate TGFβ1-induced TGFBIp expression by regulating H3K4me1/3." (PMID 26553048, 2015). "Second, TGFβ-1 gene expression changes of hMSC were detected by qPCR before and after the infection target gene." (PMID 26003220, 2015). "We also noted changes in the expression of transforming growth factor-1 (tgfβ1) in the SN starting at 7 days post-infection (dpi) that was sustained through 21 dpi, coupled with increases in arginase-1 (arg1) and csf1, M2 markers for microglia." (PMID 25861024, 2015). "Regulatory molecules like Foxp3 and TGFβ1 indeed have been reported to regulate immune responses during infection thereby preventing excessive inflammation and tissue damage." (PMID 24885723, 2014). "AdHNF4α infection of primary hepatocytes that had been treated by TGFβ1 for 48 h decreased miR-21 levels, along with a significant reduction in the mRNA transcript levels of vimentin and a noticeable increase in the mRNA transcript levels of E-cadherin." (PMID 25303175, 2014). "At 6 hours post-infection (p.i.)many of the interaction partners of Tgfb1 showed opposing regulation in BALB/c and CBA/Ca mice." (PMID 22563306, 2012). "Strikingly, expression of Tgfb1 was significantly higher in BALB/c than in CBA/Ca mice both before infection and at 6 hours p.i.." (PMID 22563306, 2012).
infection (continued). "Genotypic frequencies and associations of SNPs in IL10, IL10RA/B, TGFB1, and SLC11A1 with MAP-infection status." (PMID 20398313, 2010). "LTA -+252 and CCC, TNFA-308 and CCC, IL10-819 rs1800871 and CCC, TLR4 haplotype D229G/T399I with protection from CCC, TIRAP S180L (rs8177374) and rs8177376 (strong linkage disequilibrium) with CCC, IL18 rs360719 and infection, IL17A rs4711998 and infection, TGFB1+10 rs1800470 with infection." (PMID 40297326, 2025). "Consequently, anti-inflammatory cytokine IL-10 and transforming growth factor beta 1 (TGF-β1) are inhibited during early infection." (PMID 40732121, 2025). "The expression levels of Tgfb1, Smad3, type IV collagen gene, and type VI collagen gene in diaphragms were evaluated at protein and mRNA levels using Western blot and q-PCR at different days post-infection." (PMID 37834451, 2023). "However, many pieces are lacking for complete elucidation of the mechanisms involving TGFB1 participation in the infection, intraepithelial lesion development, and cervical cancer establishment." (PMID 36611878, 2022). "In the current studies, neuronal production of TGFb1 was not assessed, but we documented production by infiltrating inflammatory cells associated with both innate and adaptive immune responses to infection." (PMID 36016413, 2022). "However, the brains of IL-10-/- mice had a higher percentage of ILC3 cells producing TGFβ1 3 days after infection, and by day 5, both the number and percentage of TGFβ1-positive ILC3s were higher in IL-10-/- mice than WT mice." (PMID 36016413, 2022). "The study further examined different key immune genes such as the transcript level of tumor necrosis factor-alpha (TNFα), interleukin-6 (IL-6), interleukin-8 (IL-8), interleukin-10 (IL-10), interleukin-1 beta (IL-1β), and transforming growth factor-beta 1 (TGFβ1) during the early phase of infection." (PMID 36145441, 2022). "Cells isolated 3 and 5 days after infection from the CLNs, where the immune response is induced, and from brains identified as ILC3s (lineage-IL7Ra+RORgt+) were assessed for production of TGFβ1 by intracellular cytokine staining." (PMID 36016413, 2022). "The host response to infection could be regulated by TGFβ1 with the help of a cytokine storm and the presence of TNF, IL-1β, and IL-6." (PMID 33693030, 2021). "Thus, epithelial TGFβ1 signaling is likely the initiator of the fibrotic response to infection; in other models, TGFβ1 signaling from epithelial cells alone is sufficient to drive a fibrotic response to injury." (PMID 32227630, 2020). "Moreover, previous publications demonstrated that the Specific protein 1 (SP1) binding motifs are particularly enriched in TGFB1 promoter and that one of them modulates TGFB1 expression in various models, at steady state and upon infection." (PMID 29950699, 2018). "To determine what cytokines might be promoting the increased IL-17 responses in IL10SD mice, we looked at gene expression of IL-6, IL-23, TGFβ1 and IL-1β 1 week after infection of control and IL10SD mice." (PMID 23555256, 2013). "This reduction in the level of the immunosuppressor TGFB1 would lower the threshold for triggering the induction of a variety of immunologically relevant genes, resulting in a faster and more robust response to infection." (PMID 23324411, 2013). "Since we observed heightened bioactive TGFβ1 from mLN cells and within the colon at the chronic phase of infection, we speculate that TGFβ1 might have a role in the induction of gut-homing CD4+FoxP3+Tregs from naïve precursors." (PMID 21858239, 2011). "In parallel, we determined that HIV-1-related protein expression alone, in complete absence of viral replication and infection, is sufficient to induce atrogin-1 and TGFβ1 gene expressions, two factors strongly implicated in muscle catabolism." (PMID 18439274, 2008).
infection (continued). "Besides general information related to pregnancy and placenta, to search for available literature suitable for the title and content of this review, the following keywords were used in PubMed: “TGF-β1” or “TGFbeta1” or “transforming growth factor beta 1”, “virus”, “infection”, and “pregnancy”." (PMID 37047462, 2023). "Among other functions, TGFβ1 stimulates type I collagen production, therefore an increase of this factor might explain the abnormal matrix deposition that occurs in the periosteum during an infection." (PMID 36483565, 2022). "Overall, our results indicate that infections may enhance IL-13/TGFβ1 pathway-mediated fibrosis." (PMID 34858903, 2021). "Meningitic E. coli could subvert this TGFβ1-regulated barrier homeostasis during the infection." (PMID 34281571, 2021). "These dynamic changes in the exosomal miRNA composition, and potentially in other exosomal components as well, might have differentially affected immune cell behavior, such as levels of Tgfb1 expression in macrophages during the early (4 h) vs. late (14 days) phase of infection." (PMID 33396228, 2020). "Interestingly, TGFβ1 tripled its expression in 8/8 hamsters during infection." (PMID 30333964, 2018). "However, when the immune response is regulated by TGFβ1 and the infection is effectively established at ID30, its expression is negatively regulated, due to the fact that the macrophages and fibroblasts, as its main sources, are in a context in which the production of EGF is diminished." (PMID 30333964, 2018). "The expression levels of PDGF, EGF, FGF, and TGFβ1 were calculated by the ΔΔCT method and expressed as the mean ± SD of the number of times that each factor was induced with respect to healthy skin before infection (ID0), during the development of the lesion (ID15 and ID30)." (PMID 30333964, 2018). "Notably, based on the analysis of the data, we hypothesize that up-regulated TGFβ1, involved with induction of fibrosis during infection, may work through SMAD2/3/4 signaling." (PMID 27661612, 2016). "It is unclear if this is due to up-regulation of these genes in SA24T0 or down-regulation in EC24T0, but the involvement of TGFB1 in immunosuppression suggests that regulation of these genes may have a profound effect on the ability of the mammary gland quarter to respond to infection." (PMID 23324411, 2013). "Interestingly, Desai and coauthors did not detect the active form of TGFβ1 in the epididymis, suggesting activation of stored TGFβ1 might be restricted to distinct situations, such as infection or inflammation of the epididymis." (PMID 24236189, 2013). "Compared with Ad-GFP–infected cells, Ad-TET3 infection significantly enhanced TET3, STAT3, and H3K4me3 occupancy at the TGFB1 promoter." (PMID 40794443, 2025). "Increased transcription of collagen triple-helix repeat complex (cthrc) and alpha smooth muscle actin (α-sma) suggested the participation of activated fibroblasts in ΔadsA infection as did the combination of increased IP-10, IL-6, MCP-1 and TGFB1 29,30." (PMID 39134708, 2024). "In accordance with our findings, infection of OLMECs with BTV resulted in the upregulation of ENSOART00020004532 (CXCL1) expression, whereas the expression of TGFB1 was significantly downregulated." (PMID 39334220, 2024). "Two well-known targets of miR-21 and miR-146a, transforming growth factor beta-1 (TGFB1) and sprouty homolog 2 (SPRY2), were already found downregulated in THP1 cells during early infection." (PMID 37424776, 2023). "In sheep, the TGFB1 and COL1A1 genes were upregulated during the acute phase of infection in peripheral blood mononuclear cells (PBMC), and at later stages in liver tissue (8 wpi)." (PMID 34122452, 2021). "Infection significantly increased the expression of ACE2, TMPRSS2, ADAM17, TGFB1, CTGF, VEGFA and FN1 but resulted in trends towards decreases in TIMP3 (p = 0.083) and AGF (p = 0.086) in A549 cells compared to control cells." (PMID 32664949, 2020).